TWIST1 (twist family bHLH transcription factor 1)
Diseases named in the same sentence as TWIST1 in open-access papers (continued):
Sharing a sentence is not in itself a finding about the gene and the disease.
cancer (continued). "Previous studies have reported that activation of Rac1 mediated Twist1-induced cancer cell migration." (PMID 24565050, 2013). "All of the miRNAs shown to repress TWIST1 expression have been demonstrated to be involved both in embryonic development and cancer." (PMID 23741524, 2013). "TWIST1 is a key player in tumorigenesis and metastasis and its overexpression has mostly been correlated with progressed stages of cancer and drug resistance." (PMID 23741524, 2013). "The elevated Twist1 expression is found to be positively correlated with aggressiveness of cancer and poor survival rate." (PMID 22245869, 2012). "Our mouse model will be useful to identify agents that target TWIST1 for the treatment of human cancer." (PMID 22654667, 2012). "A novel function of Twist1 has been reported in the development of acquired chemoresistance in human cancer cells." (PMID 22245869, 2012). "Twist1 protein expression is usually undetectable in most adult tissues, but has been shown to be overexpressed in cancers including prostate, bladder pancreatic, osteosarcomas, melanomas and breast." (PMID 22654667, 2012). "The bHLH transcription factor TWIST1, which is essential in developmental processes, such as gastrulation, has been shown to be oncogenic in various cancers." (PMID 22967435, 2012). "Blockage of IL8 signaling by IL8 neutralizing antibodies or receptor inhibition reduced the invasiveness of both breast epithelial and cancer cells, indicating that TWIST1 induces autonomous cell invasion by establishing an IL8 antocrine loop." (PMID 22891766, 2012). "How these pathways, involving well-known cancer-related genes, are connected to TWIST1 expression in relation to disease progression in LNN/ER-positive cancer warrants functional validation." (PMID 22967435, 2012). "Recently, a novel function of Twist1 has been reported in the development of acquired chemoresistance in human cancer cells." (PMID 22245869, 2012). "It is known that Twist1 plays an important role in epithelial mesenchymal transition (EMT) in various forms of malignant tumors and high levels of Twist1 are positively correlated with the metastatic potential." (PMID 22969750, 2012). "In support of the relevance of EMT in vivo, the presence of the tagged-TWIST1 transgene in both the epithelial and fusiform cancer cell contingents demonstrated that mesenchymal cells arose through transdifferentiation of their epithelial counterparts." (PMID 22654675, 2012). "It is likely that the same Twist1-activated regulatory hierarchies are important in the development of various cell types, including osteoblast, neural crest cells, and cancer cells." (PMID 22242143, 2011). "In humans, highly metastatic and chemotherapeutic resistant cancers including breast, glioma, prostate, melanoma, and neuroblastoma express high levels of TWIST1." (PMID 22242143, 2011). "Additional Twist1 target genes involved in cell migration include N-cadherin, identified in cancer cells, and Zyxin, identified in ECC mesenchymal cells." (PMID 22242143, 2011). "Elucidation of Twist1 transcriptional hierarchies regulating cell proliferation and migration will further the understanding of the molecular mechanisms by which Twist1 functions in heart development and cancer progression." (PMID 22242143, 2011). "The correlation of Twist1 expression with increased cell proliferation and migration of cancer cells, and also in diseased heart valves, is likely to be related to its functions in embryonic mesenchymal populations, including ECC mesenchymal cells." (PMID 22242143, 2011). "The widespread expression of Twist1 in various cancer phenotypes suggests its action upon a diverse set of downstream target genes, depending upon the tissue, to elicit a variety of cellular responses." (PMID 22184289, 2011).
cancer (continued). "The second is supported by the unique role played by TWIST1 in promoting cell dedifferentiation, migration and proliferation in processes like cancer or Epithelial-Mesenchymal Transition (EMT)." (PMID 21814570, 2011). "Additional Twist1 candidate target genes identified by microarray, Trib3 and Serpinb9b, promote proliferation of cancer cells and dendritic cells, respectively." (PMID 22242143, 2011). "Evidence also indicates that TWIST1 contributes to cancer cell dissemination by promoting EMT and increasing cellular invasiveness." (PMID 22060274, 2011). "The AKT signaling pathway has been reported to promote TWIST1 expression in different carcinoma cells." (PMID 22060274, 2011). "TWIST1 is a helix-loop-helix transcription factor, regulator of embryonic morphogenesis, and highly expressed in many types of human cancer." (PMID 20976069, 2010). "We previously showed that the bHLH transcription factor TWIST1 which orchestrates carcinoma metastasis through an epithelial mesenchymal transition (EMT) is upregulated in GBM and promotes invasion of the SF767 GBM cell line in vitro." (PMID 20646316, 2010). "A central feature of TWIST1-mediated EMT is the repression of the epithelial marker E-cadherin, and activation of the mesenchymal marker N-cadherin, a hallmark feature of carcinoma EMT termed the "cadherin switch"." (PMID 20646316, 2010). "Many genes related to carcinoma EMT were also up-regulated by TWIST1 in GBM indicating potential mechanistic overlap between the two processes." (PMID 20646316, 2010). "Our lab has identified an important role for the pro-mesnenchymal gene, TWIST1, in GBM invasion through activation of properties similar to epithelial-mesenchymal transitions(EMT) associated with carcinoma invasion and metastasis." (PMID 20847921, 2010). "TWIST1 is a central regulator of mesenchymal change in carcinoma but its relevance to invasion and mesenchymal change in GBM models has not been studied." (PMID 20646316, 2010). "Additionally, Twist1 has been identified to correlate with tumorigenesis, angiogenesis, and poor prognosis in various human cancers." (PMID 40344465, 2025). "It would be interesting to investigate whether localized anti-EVs therapy combined with systemic anti-Twist1 blockade could synergize to exert therapeutic effects on cancer progression and CID." (PMID 40963917, 2025). "TWIST1, a bHLH transcription factor, regulates mesenchymal specification, differentiation, proliferation and migration during development and in diseases such as cancer." (PMID 41246007, 2025). "Future post-mortem studies in cancer patients will help verify whether Twist1 expression changes in the mPFC, and accompanied by abnormal neuronal morphogenesis." (PMID 40963917, 2025). "Interestingly, HOTTIP facilitates cancer cell metastasis via Twist family bHLH transcription factor 1 (TWIST1)-WDR5-HOTTIP axis that regulates HOXA9 chromatin." (PMID 40616679, 2025). "Our findings reveal a critical pathway through which UCHL1-mediated deubiquitination sustains Twist1 stability, revealing a novel posttranslational regulatory axis involved in cancer metastasis and progression and highlighting promising therapeutic targets for metastatic NSCLC." (PMID 41469388, 2025). "Given that M2 macrophages are known to induce epithelial‐mesenchymal transformation (EMT) in cancer cells, we explored the correlation between VSIG4 and several biomarkers associated with EMT processes (MMP9, SNAI1, SNAI2, VIM, TWIST1, TWIST2, CDH1, CDH2) in CRC through the TIMER2.0 website." (PMID 40405491, 2025). "TWIST1 and SNAI2 as mesenchymal markers have been implicated in aggressive behavior cancers." (PMID 40332096, 2025). "In addition, stiff ECMs trigger the nuclear localization of β-catenin and Twist1, which induces cancer progression." (PMID 40124511, 2025). "TWIST1 has been primarily investigated in cancer for its role in EMT." (PMID 39042469, 2024).
cancer (continued). "We integrated analyzed the function of P4HA3 among 33 types of cancers, and found that P4HA3 was associated with proliferation markers (PCNA and MKI67), EMT markers (VIM, TWIST1, SNAI1, SNAI2, FN1 and CDH2), extracellular matrix (ECM) markers (MMP9, MMP7, MMP2 and MMP14)." (PMID 39504328, 2024). "TWIST1 gene encodesTwist related protein-1, a key transcription factor implicated intumor progression via EMT and ECM stiffness and our findings suggest that its expression is more specific tothe cancer cell phenotype." (PMID 39398183, 2024). "In co-cultures of platelets and cancer cells, platelets have been shown to induce the mesenchymal phenotype of cancer cells, as characterized by upregulation of Twist1 and reductions in E-cadherin, which in turn enhanced cancer cell motility and platelet pro-aggregation status." (PMID 39456628, 2024). "For early-stage cancers, DNA methylation-based biomarkers are of particular importance Recent scientific work indicates the high potential of hypermethylated genes TWIST1, VIM, ZNF671, OTX1, and IRF8 for early diagnosis and PTK2, AHNAK, and DAPK for BC prognosis." (PMID 39685620, 2024). "Similarly, PER2 affects cancer metastasis by repressing EMT-related genes like TWIST1 and SLUG through interactions with polycomb proteins and HDAC2." (PMID 39566400, 2024). "Furthermore, it has been reported that the knockdown of Twist1 sensitizes cancer cells to chemotherapy." (PMID 38473317, 2024). "Additionally, another study demonstrated that PEVs from patients with colorectal cancer induced Twist1 and vimentin expression in all cancer cell lines studied, whereas PEVs from healthy controls did not." (PMID 39183323, 2024). "Finally, Twist1 and Snail are known to increase the stemness of cancer cells, another important process that enables cancer cells to self-renew, resist chemotherapy, and metastasize." (PMID 39000112, 2024). "Cancer cells also proliferate, migrate, and invade when TWIST1 was activated." (PMID 37215997, 2023). "Moreover, ginsenosides inhibit the NF-κB-mediated activation of cancer metastasis and immune resistance, significantly attenuating the expression of MMPs, Snail, Slug, TWIST1, and PD-L1." (PMID 37047092, 2023). "In this case, EndMT was mediated by TWIST1 and the NFκB factor p65, which we and colleagues previously showed could together regulate IL-8 and matrix metallopeptidase production in cancer." (PMID 38139368, 2023). "In cancer cells, TWIST1 can positively regulate the migration and invasion of cancer cells." (PMID 37115802, 2023). "Thus, to dissect the mechanism controlling TWIST1 stability will provide important clues for potential therapeutic strategy to conquer chemo‐resistance and cancer metastasis in TNBC." (PMID 36782089, 2023). "Furthermore, a high Twist1 expression has been found to increase cancer cell resistance to anoikis using in vitro studies." (PMID 36732432, 2023). "TWIST1 expression was found in several cancers and promoted cancer cell invasion and metastasis." (PMID 36744005, 2023). "Significant TFs identified within the enhancer regions include SMAD2:SMAD3, EWS-ERG fusion, TWIST1, and TEAD3, which play important roles in regulation of transcription in transforming growth factors and embryonic development and are associated with cancers." (PMID 36936794, 2023). "Taken together, these results imply that the suppression of Twist1 protein levels by pelitinib alters E-cadherin and N-cadherin expression, which may prevent further cancer progression." (PMID 37495969, 2023). "Abnormal expression of TWIST1 has been frequently observed in many types of cancers." (PMID 35052775, 2022). "Moreover, lysine residue 73 (K73) in human TWIST1 is identified as the critical site for ubiquitination that modulates protein homeostasis, cancer cell growth, migration and invasion of TNBC." (PMID 36115849, 2022).
cancer (continued). "miR-145-5p has been found to suppress cancer cell proliferation, invasion, stemness, chemotherapy, and radiation sensitivity in patients with PCa by targeting different regulators such as DNMT3a, TWIST1, ITPR2, AR, and NMT3b." (PMID 35368699, 2022). "Overexpression of SNAI1 and TWIST1, encoding key regulators of epithelial-to-mesenchymal transition (EMT), significantly contributes to cancer development and has been directly related to chemoresistance and poor prognosis in several cancer types." (PMID 36140779, 2022). "Previous reports have posited that targeting of molecules downstream of activin A such as Twist1 or JNK ameliorates cancer-induced muscle cachexia and may prolong survival in animal models of PDAC42,43." (PMID 35102236, 2022). "For further identifying whether RBX1 could modulate the expression of TWIST1, we first looked at the mRNA and protein levels of TWIST1 in overexpressed or RBX1 knockdown TNBC cancer cells." (PMID 35802537, 2022). "In HCC, MYBL1 is shown to promote cancer cell proliferation by activating TWIST1 transcription." (PMID 35681031, 2022). "TWIST1 overexpression is frequently detected in several cancers also including BC." (PMID 35804889, 2022). "Since TWIST1 and β-catenin both play important role in cancer formation and progression, we hypothesized that TWIST1 may regulate β-catenin expression and function due to the correlation of TWIST1 and CTNNB1 in our EMT assay." (PMID 36123378, 2022). "Thus EMT-associated transcription factors (EMT-TFs), such as TWIST1/2 and SNAIL1/2, can activate EMT and promote cancer metastasis." (PMID 36115849, 2022). "Consequently, there is an interdependent relationship between the expression of BMI1 and TWIST1 in cancer initiation, differentiation, self-renewal, stemness, EMT, and CSC-mediated metastasis." (PMID 36553636, 2022). "Therefore, TWIST1 can mediate cancer cells’ drug resistance through the regulation of pro- as well as anti-apoptotic markers." (PMID 36474162, 2022). "Furthermore, through the TCGA database we found that the mRNA expression levels of ZEB2 and TWIST1 were positively correlated across cancer malignancy stages (G1–G4) in 600 CRC patients." (PMID 35884488, 2022). "Treatment of Rafoxanide, instead, could inhibit cancer cell survival and inhibit the expression of pro-EMT transcription factors Twist1, Snail and Slug in cancer cells." (PMID 36123332, 2022). "Thus, Twist1 functions in mechanotransduction in cancer cells and plays an important role in cancer progression." (PMID 35205794, 2022). "Since stemness markers determine self-renewing cell populations with CSC characteristics in various types of cancers, we next examined the effect of TWIST1 overexpression on the induction of stemness genes SALL4, OCT4, NANOG and SOX2 in KYSE-30 and YM-1 ESCC cells." (PMID 36474162, 2022). "Many studies eported that TWIST1 could maintain the stemness of cancer cells and is necessary for cancer cell dissemination, proliferation and metastases 31–34." (PMID 36123378, 2022). "Indeed, Twist1 is significantly increased in skeletal muscles of several mouse models of cancer cachexia." (PMID 35441960, 2022). "Additionally, BHMPS effectively decreased the levels of serum-stimulated EMT-activating transcription factors, including Snail, Slug, Zeb1, and Twist1, which are highly related to cancer migration and invasion." (PMID 35053535, 2022). "TWIST1 is a phospho-protein and multiple phospho-residues are necessary for its stability, nuclear translocation and transcriptional regulation, as per previous cancer studies." (PMID 35781329, 2022). "A study of TWIST1 mRNA expression in 25 feline mammary gland tissues (7 normal glands, 3 hyperplastic lesions, 1 benign tumour and 14 carcinomas) found that the carcinomas had significantly lower TWIST1 mRNA levels than benign lesions and disease-free mammary glands." (PMID 36288160, 2022).
cancer (continued). "Together, these data suggest that the TMPRSS4/TWIST1–SLUG/SOX2 axis could be exploited as a target for anti-cancer therapy." (PMID 34809669, 2021). "Twist1 overexpression has been found to induce EMT of cancer cells." (PMID 34830907, 2021). "Additionally, the USP1-RPS16 axis is required for metastasis by increasing the expression of Twist1 and Snail, two well-studied masters of cancer metastasis via activating epithelial-mesenchymal transition (EMT)." (PMID 34154657, 2021). "In addition, the tumor suppressor gene SMAD4 participates in EMT, as it is known to complex with multiple TFs (e.g., SNAIL, SLUG, TWIST1), in various types of cancer, promoting the repression or activation of target genes." (PMID 34768901, 2021). "TWIST1 is overexpressed in various cancer cells including osteosarcoma cancer cells." (PMID 34224315, 2021). "In addition, Twist1 is also reported to promote the cancer stem cell phenotype, inhibit apoptosis, and contribute to chemotherapy resistance." (PMID 33626096, 2021). "Researchers have yet to determine the extent to which EMT, proliferation, apoptosis, and inflammation in cancer are regulated via Twist1, and whether these processes are independent." (PMID 34577566, 2021). "Successful inactivation of Twist1 in cancer cells by siRNA or chemotherapeutic approaches has been reported, and inhibitors targeting either the upstream regulator or downstream effector of Twist1 signaling have also been identified for cancer therapy." (PMID 33626096, 2021). "SNAI2 and TWIST1 induce the stemness property of cancer cells." (PMID 34339740, 2021). "Various studies have also demonstrated the role of TWIST1 in cancer stemness." (PMID 34277708, 2021). "Further, high levels of TWIST1 in resected human CRC specimens were associated with the expression of P-gp, a transmembrane glycoprotein conferring multidrug-resistance phenotype to cancer cells." (PMID 34768901, 2021). "PPD can also exhibit its anti-cancer effects by targeting the STAT3/Twist1 pathway." (PMID 34830907, 2021). "In addition, harmine shows anti-cancer activity via Twist1 suppression in K-RAS mutant NSCLC mouse models." (PMID 33768509, 2021). "Because of the importance of Twist1 in metastasis, we also examined the expression of EMT markers E-Cadherin, N-Cadherin, and Vimentin in harmine-treated cancer cells and demonstrated that reduced Twist1 affects the Twist1-regulated downstream targets involved in EMT." (PMID 33626096, 2021). "TWIST-1 (coding twist-related protein 1) is involved in epithelial-mesenchymal transition and cell-migration processes, and is overexpressed in several human cancers, including GC." (PMID 32117120, 2020). "Therefore, MYC and TWIST1 generally appear to cooperate in human cancer to elicit a cytokinome that enables metastasis through crosstalk between cancer and immune microenvironment." (PMID 31933479, 2020). "Based on the gene expression analysis, FD extract had reduced the expression of the TWIST1 and RAC1 genes associated with epithelial-mesenchymal transition (EMT) and had significantly downregulated the COX-2 and EGFR genes associated with cancer angiogenesis, metastasis, and chemoresistance." (PMID 32104177, 2020). "Stable inhibition of miR-145-5p in immortalized prostate PNT1A epithelial cells and in PC3 cancer cells led to increased TWIST1 expression and consequently to stemness properties (self-renewal in PNT1A and PC3 cells) associated with increased cell migration in PNT1A cells." (PMID 33227047, 2020). "For example, EMT-TFs such as Snai1/2 and Twist1 also regulate cancer cell survival and cancer drug resistance, and it is currently unknown whether cell survival and drug resistance are regulated independently of EMT." (PMID 32300252, 2020).